IGF1 (insulin like growth factor 1)
Diseases named in the same sentence as IGF1 in open-access papers (continued):
Sharing a sentence is not in itself a finding about the gene and the disease.
breast cancer (953 papers, 1992 to 2026). A primary or metastatic malignant neoplasm involving the breast. "Circulating free IGF-1 increases the risk of many cancer types including colorectal, prostate, and breast cancer." (PMID 41376649, 2026). "Without these adjustments, it is difficult to tease out the independent effect of acromegaly or GH/IGF-1 excess on breast cancer risk." (PMID 41293738, 2025). "Lower levels of insulin and IGF-1 reduce cellularproliferation and mutation risk, while decreased estrogen exposureis particularly protective against breast cancer development." (PMID 41183009, 2025). "The IGFBP-3 A-202C polymorphism, especially the CC genotype, is strongly associated with elevated serum IGFBP-3 and IGF-1 levels and increased breast cancer risk, highlighting its potential as a biomarker for breast cancer screening and risk stratification." (PMID 40493660, 2025). "Musculoskeletal pain in breast cancer patients has been significantly associated with decreases in IGF‐1 and vitamin D concentrations over the first six months of AI treatment." (PMID 40557725, 2025). "TheGH/IGF-1 axis is critical for normal mammary gland development and remodeling, but chronic exposure to elevated IGF-1 levels is strongly associated with increased breast cancer risk." (PMID 40243654, 2025). "Both IGF1 and G‐CSF have been implicated in influencing dormant cell behavior; specifically, IGF1 administration promotes proliferation of dormant breast cancer cells, as evidenced by increased Ki67+ DCCs." (PMID 41020040, 2025). "By examining the IGFBP-3 A-202C polymorphism in the context of both IGFBP-3 and IGF-1 serum levels, we clarify the role of this polymorphism as a biomarker for early breast cancer detection, particularly in Palestinian women." (PMID 40493660, 2025). "Ultimately, we found that knockdown of ANXA2 in breast cancer-associated fibroblasts not only affected the expression of SPOCK1 but also led to a decrease in IGF1 expression." (PMID 40837013, 2025). "In breast cancer models, the IGF1R regulates the expression and localization of YAP, a major mediator of the Hippo pathway, while YAP expression in turn up-regulates IGF1, a crucial mechanism underlying breast cancer stem cell progression." (PMID 38892104, 2024). "On the other hand, high levels of IGF1 in the plasma have been positively associated with different tumor types, including colorectal cancer, breast cancer, prostate cancer, thyroid cancer and possibly malignant melanoma and multiple myeloma." (PMID 38892104, 2024). "Previous research has established a connection between elevated IGF-1 levels and obesity, as well as a link between IGF-1 and a higher risk of developing breast cancer." (PMID 39339753, 2024). "IGF1 is an essential hormone involved in regulating cell growth and differentiation, and its dysregulation has been linked to various cancers, including breast cancer." (PMID 38623138, 2024). "Increased levels of insulin-like growth factor 1 are associated with cancer development, and circulating IGF1 is positively associated with breast cancer risk." (PMID 39042294, 2024). "Cluster 3 displayed three genes (Cxxl12, Igf1, and Myc), associated mainly with cell proliferation, transcription, breast cancer, transcriptional dysregulation in cancer, and proteoglycans in cancer." (PMID 37243196, 2023). "For example, elevated IGF-1 has been shown to correspond to a 69% increase in colorectal cancer risk, a 49% increase in prostate cancer risk, 65% increase in breast cancer risk, and a 106% increase in lung cancer risk (relative risks)." (PMID 37958602, 2023). "High levels of circulating type 1 IGF (IGF-1) and hyperinsulinemia have been associated with higher breast cancer risk and poor prognosis." (PMID 37373357, 2023). "High IGF-1 levels were found to be a risk factor for breast cancer in epidemiologic studies as well as a mitogen for many breast cancer cell lines." (PMID 36835533, 2023).
breast cancer (continued). "Elevated levels of IGF-1 are associated with an increased risk of both the development and recurrence of breast cancer, primarily due to its roles in myogenesis and anti-apoptotic activities." (PMID 38406785, 2023). "A portion of studies have reported that serum IGF-1 level is a risk factor for predicting recurrence after surgery or drug therapy in breast cancer, hepatocellular carcinoma, and gastric cancer." (PMID 36831629, 2023). "During pregnancy different factors such as reduced levels of estrogens and IGF-1, elevated level of progesterone, androgen, corticotropin-releasing factors can individually or collectively play a crucial role to reduce the breast cancer risk in women." (PMID 37173714, 2023). "The IGF-1 protein has been most closely associated with breast cancer progression because it has mitogenic and anti-apoptotic effects on mammary epithelial cells." (PMID 38202341, 2023). "A pooled analysis of 17 studies demonstrated that higher levels of circulating IGF-1 are associated with increased risk of breast cancer, with this being especially true for hormone receptor-positive (HR+) breast cancer." (PMID 36331687, 2023). "Several previous genetic studies (GWAS, etc.)have showed association of rs1079866 INHBA with AAM, Tanner stage in girls, height adult, IGF-1 level, breast cancer risk." (PMID 37511900, 2023). "•Higher serum CRP, testosterone, and IGF-1 levels were associated with both the elevated breast cancer risk and mortality." (PMID 38000092, 2023). "Elevated IGF1 levels are specifically associated with increased risk of breast cancer, and high IGF1 levels are associated with increased breast cancer mortality, with a hazard ratio of 3.1." (PMID 38136416, 2023). "Previous large epidemiological studies have found statistically significant associations between IGF-1 and breast cancer only in premenopausal women; in postmenopausal women the associations were weaker and not statistically significant." (PMID 35115550, 2022). "In our animal model, increased stromal Igf1 expression expanded the MaSC population in HT animals before puberty, thereby establishing increased mammary cancer risk during the early stages of mammary gland development." (PMID 36010633, 2022). "The purpose of the current study was to investigate the protein expression of ANGPTL4 and IGF-1 in primary breast carcinoma tissue and its association with breast cancer molecular subtypes in patients younger than 45 years." (PMID 35366286, 2022). "The association between IGF-1 and breast cancer was confirmed by cohort and Mendelian randomization studies, likely via biological mechanisms through mitogenic and anti-apoptotic effects." (PMID 35578620, 2022). "A strong positive correlation between circulating levels of IGF-1 and breast cancer risk has been observed in many studies, specifically in premenopausal women." (PMID 36556357, 2022). "The negative association between BMI and overall, as well as ER+ breast cancer risk was attenuated after adjustment for HDL cholesterol or IGF-1, which influenced the risk of these cancers independently of obesity." (PMID 36558416, 2022). "Suggestive associations were also detected between elevated circulating IGF-1 and higher overall (OR = 1.01, 95% CI 1.00–1.02) and ER+ (OR = 1.01, 95% CI 1.00–1.02) breast cancer risk." (PMID 36558416, 2022). "To do this, we treated breast cancer cells with exogenous IGF1 and found that IGF1 caused an elevation of GASP1 expression." (PMID 36042202, 2022). "Early-adulthood body size is associated with IGF-1, an intermediate marker for breast cancer, and overweight women have lower IGF-1 levels than lean women in youth and adolescence." (PMID 35277131, 2022). "Another finding in our study indicate that ultralow risk tumors exhibit lower expression scores of the IGF1‐pathway‐associated module, which is involved in breast cancer development and progression." (PMID 35179782, 2022).
breast cancer (continued). "Epidemiological analyses conducted over the past twenty-five years identified IGF1 as a risk factor for breast cancer." (PMID 35432218, 2022). "In postmenopausal women, IGF‐1 levels as well as oestrogen levels have been posited as potential links between obesity and breast cancer risk." (PMID 35049043, 2022). "The BMI-adjusted estimates of HDL cholesterol and IGF-1 for overall breast cancer risk were OR 1.07 (95% CI 1.02–1.13) and OR 1.02 (95% CI 1.00–1.04), respectively and for ER+ breast cancer, OR 1.07 (95% CI 1.00–1.14) and OR 1.02 (95% CI 1.00–1.04)." (PMID 36558416, 2022). "A recent human study shows that increased circulating Igf1 levels are associated with increased breast cancer risk in a large cohort (n = 206, 263) of women." (PMID 36010633, 2022). "Previous systematic reviews and meta-analyses also suggested that the high level of IGF1 in circulation is associated with an increased risk of breast cancer." (PMID 35250656, 2022). "Many studies have suggested that IGF-1 is involved in the development of breast cancer, is associated with an increased risk of premenopausal breast cancer, and has poor prognosis including decreased breast cancer-specific survival." (PMID 35277131, 2022). "For cancer biomarkers, a previous observational and MR study found positive associations between levels of IGF-1 and overall breast cancer risk in women in the UKB, which agrees with our findings." (PMID 36424572, 2022). "Epidemiological studies support that the IGF pathway plays an important role in breast cancer risk, and a link between IGF signaling and breast cancer initiation is supported mechanistically by studies using IGF-1 transgenic mice." (PMID 36556357, 2022). "IGF-1 has long been implicated in breast cancer due to the role of IGF-1 receptors in activating the AKT and mitogen-activated protein kinase signalling networks in tumour growth." (PMID 36424572, 2022). "CCK-8 assay, together with EdU assay suggested that IGF-1 reversed the inhibition of breast cancer cell proliferation caused by the knockdown of HM13." (PMID 36153332, 2022). "Epidemiological studies suggested a strong association between circulating serum IGF-1 levels and the risk of several cancers such as breast cancer." (PMID 36498723, 2022). "Two SNPs in two genes (MBOAT rs13272159 and NPY rs16131) showed an effect modification on the association between IGF-1 serum concentration and breast cancer risk (Pinteraction < 0.05, adjusted Pinteraction < 0.20)." (PMID 35115550, 2022). "The increased production of cells in the breast due to increased IGF-1 is thought to lead to increased breast density and eventually to an increased risk of breast cancer." (PMID 35836268, 2022). "Another important marker in breast cancer is insulin-like growth factor-1 (IGF-1), which is a polypeptide encoded by the IGF-1 gene located on chromosome 12." (PMID 35366286, 2022). "In post-menopausal women, there was a weaker positive association between IGF-1 and breast cancer risk (HR per 5 nmol/L increment: 1.07; 95% CI: 1.01, 1.12)." (PMID 33864017, 2021). "Circulating estrogens, androgens, and insulin-like growth factor 1 (IGF-1) have been associated with an increased risk of breast cancer in women, whereas sex hormone-binding globulin (SHBG) is inversely associated with the risk." (PMID 34607837, 2021). "An analysis of UK Biobank data showed that high IGF-1 concentration in premenopausal and postmenopausal females is associated with breast cancer risk increase." (PMID 34530525, 2021). "The upregulation of p21cip1 mRNA level by IGF-1 was also associated with the MAPK-ERK1/2 pathway in MCF-7 human breast cancer cells." (PMID 34093234, 2021). "In pre-menopausal women, there was a significant positive association between IGF-1 concentration and breast cancer risk (HR per 5 nmol/L increment: 1.18; 95% CI: 1.02, 1.35)." (PMID 33864017, 2021).
breast cancer (continued). "Breast cancer mortality is increased in patients affected by metabolic disorders associated with dysregulation of the Insulin-like growth factor-1 (IGF-1) axis, like obesity and type-2 diabetes." (PMID 33557316, 2021). "IGF1 is also a high risk factor for several cancers, such as prostate cancer, breast cancer, lung cancer, gastric cancer, and colon cancer." (PMID 34544905, 2021). "Circulating lipids and insulin-like growth factor 1 (IGF-I) have been reliably associated with breast cancer." (PMID 34583967, 2021). "Circulating IGF-1 levels are also associated with breast cancer risk, with pooled data from 17 prospective studies demonstrating a positive association between IGF-1 levels and estrogen-receptor-positive cancer risk." (PMID 33910628, 2021). "Epidemiologic studies have shown that a high circulating concentration of IGF-1 is associated with an increased risk of prostate cancer and breast cancer." (PMID 33429867, 2021). "Many observational studies have been conducted to investigate if there is a link between IGF-1 signalling and breast cancer risk." (PMID 33816477, 2021). "Elevated insulin levels can cause high insulin growth factor-1 (IGF-1) bioavailability, leading to the occurrence and proliferation of breast cancer." (PMID 33842335, 2021). "High levels of IGF-1 are, in fact, associated with an increased incidence of several cancers, including colorectal, prostate and breast cancers, while mutations in the human IGF-1R were found to protect against age-related disorders." (PMID 34572814, 2021). "The association between diabetes and breast cancer supports the effect of insulin and IGF-1 as a mitogen and also its influences on estrogen hormone levels." (PMID 32528752, 2020). "The C allele of rs1520220 was found significantly associated with increased serum IGF1 levels and an increased risk of breast cancer in women." (PMID 32150843, 2020). "Unadjusted Kaplan–Meier curves identified that compared with patients with low IGF1, patients with high IGF1 exhibited lower cumulative incidence of all-cause mortality (1.3 vs. 2.8%, P = 0.007) and breast cancer-specific mortality (1.1 vs. 2.1%, P = 0.038)." (PMID 32974138, 2020). "Previous studies have indicated that high concentrations of IGF1 were associated with an increased risk of breast cancer, especially for premenopausal breast cancer and estrogen receptor-positive breast cancer." (PMID 32974138, 2020). "Diabetes mellitus (mainly type II) correlates with an increased risk of breast cancer, especially when associated with an elevated BMI (Body Mass Index) and with high levels of IGF-1." (PMID 33375317, 2020). "Multivariate logistic regression analysis of factors associated with IGF-1 level in HER2-positive breast cancer patients." (PMID 32391265, 2020). "Studies have shown that both breast cancer development and recurrence are associated with IGF-1 and IGFBP-3 levels in women." (PMID 33092613, 2020). "Hyperinsulinemia is another factor causing breast cancer, which encourages insulin-like growth factor (IGF–1) production and activity." (PMID 32093283, 2020). "In this study, the large prospective sample enabled us to assess the association of IGF1 and prognostic outcomes of breast cancer among specific subgroups by important risk factors and clinical characteristics." (PMID 32974138, 2020). "A growing body of epidemiological investigations has examined the association between IGF1 and the incidence of breast cancer." (PMID 32974138, 2020). "For instance, high IGF-1R expression and elevated IGF-1 circulating levels have been correlated with an increased breast cancer risk and poor prognosis in breast cancer patients." (PMID 32325700, 2020). "In conclusion, circulating IGF-1 expression in HER2-positive breast cancer patients was associated with menopausal status and IGFBP-3 level." (PMID 32391265, 2020). "Higher levels of estrogen and IGF-1 in adulthood have been associated with increased breast cancer risk." (PMID 33109223, 2020).
breast cancer (continued). "Another smaller case‐control study (4647 cases and 4564 controls) found that the IGF‐1‐increasing allele of rs1520220 in the IGF1 gene was associated with higher odds of breast cancer." (PMID 32717139, 2020). "This IGF-1/IGFBP-3 ratio is essential in determining breast cancer risk coupled with other factors, such as age, hormonal use, and family history." (PMID 32528752, 2020). "As the molecular interplay between IGF1 and leptin, as well as its association with the pathogenesis of breast cancer, was shown previously, we have also analyzed the level of leptin which was significantly decreased in the group of MSC-CA." (PMID 32093026, 2020). "Interactions between IGF1 and insulin on all-cause mortality, breast cancer-specific mortality, and breast cancer recurrencea." (PMID 32974138, 2020). "During pregnancy, in response to growth hormones, expression of ER, PR, and IGF-1 is elevated and is linked with increase in breast cancer cell proliferation." (PMID 33425733, 2020). "The risk of breast cancer was elevated across models with continuous biomarker measures except for the adjusted model for continuous IGF-1 (OR = 0.77, 95% CI 0.26–2.31)." (PMID 33092613, 2020). "Specifically, in a prospective nested control study (the Nurse’s Health Study), the relative risk (RR) of breast cancer in premenopausal women was 4.6 in the upper tertile of IGF1 values in comparison to women in the lower tertile." (PMID 33182502, 2020). "High level of IGF-1 has been associated with increased risk of breast cancer in both pre-menopausal and post-menopausal women." (PMID 31380268, 2019). "A correlation between circulating IGF-1 and the risk of developing breast cancer, colorectal cancer, lung cancer and prostate cancer has been described." (PMID 31795319, 2019). "On the contrary, high amounts of fat, saturated fat and potentially carcinogenic contaminants (pesticides, oestrogen metabolites, and growth factors including IGF-1) in dairy products can increase the risk for breast cancer." (PMID 31877693, 2019). "The miRNA-mRNA network shows that significantly deregulated miRNAs in the FS and FSO groups target genes involved in the MG development (red circles) and/or associated with breast cancer (blue circles), including Egfr, Igf-1, Igf-1R, Hif1a, Ets1, and pgr." (PMID 31689992, 2019). "In fact, women with a high circulating rate of IGF-1 have a 28% higher risk of developing breast cancer compared to women with low concentrations of IGF-1." (PMID 31284513, 2019). "The insulin/IGF-1 axis plays an important role in the association between obesity and risk of breast cancer." (PMID 29558911, 2018). "Of particular interest, IGF-1 has been most strongly implicated in breast cancer progression based on its mitogenic and anti-apoptotic activities." (PMID 29162853, 2017). "Animal models have also demonstrated that IGF-1 can obliterate the pregnancy-associated protection against breast cancer by increasing ERα activation." (PMID 28822014, 2017). "Three studies reported in 2005 by scientists in Sweden, the United Kingdom and the United States also showed an association between circulating levels of IGF-1 and the risk of breast cancer in pre-menopausal women." (PMID 28865460, 2017). "We then assessed their response to selected cytokines such as insulin growth factor 1 (IGF1) and tumor necrosis factor alpha (TNFα), which are associated with breast cancer risk." (PMID 28369883, 2017). "The circulating IGF1 (insulin-like growth factor-1) level is associated with the risk to develop breast cancer." (PMID 28384236, 2017). "A pooled data analysis of 17 studies demonstrated that women with higher circulating IGF-1 levels have a higher risk of breast cancer, and that this is especially true for ER+ (estrogen receptor-positive) breast cancer development." (PMID 28822014, 2017). "Earlier studies have identified the association of IGF-1 with the increased risk of breast cancer development." (PMID 29162853, 2017).